TNF (tumor necrosis factor)
Diseases named in the same sentence as TNF in open-access papers (continued):
Sharing a sentence is not in itself a finding about the gene and the disease.
chronic gastritis (continued). "Furthermore, in studies on chronic gastritis, it has been found that an increased SP activation can lead to an increased TNF-alpha production." (PMID 29183282, 2017). "The expression of cytokines IL-23, IL-21, TNF-α, and IL-10 did not have a significant association with the severity of chronic gastritis in this study." (PMID 29391865, 2017). "Specifically, HP infection induces chronic gastritis and local chronic inflammation, stimulating the production of response inflammatory proteins and cytokines such as C-reactive protein, tumor necrosis factor alpha (TNF-α), interleukins (IL-1, IL-6, IL-8, IL-10), and eicosanoids." (PMID 27851820, 2016). "Immunohistochemical analysis allowed us to show expression and cell localization of TNF‐α, IL‐1β, IL‐2, IL‐12‐p40 and TGF‐β‐RII proteins in the normal mucosa, and in H. pylori infected and non‐infected chronic gastritis." (PMID 26945693, 2016). "Hp− chronic gastritis samples showed weak immunostaining in the foveolar epithelium for most cases of all proteins, except TGF‐β‐RII, which showed strong expression, besides immunostaining of inflammatory cells in some cases for TNF‐α and TGF‐β‐RII." (PMID 26945693, 2016).
coagulopathy (29 papers, 2013 to 2025). "A large number of IFN cytokines such asγ, TNF, and IL-1 release activate cytotoxic T cells and macrophages, make them proliferate and activate in large numbers, produce hypercytokinemia, enhance macrophage phagocytosis, and cause coagulation disorders." (PMID 35200596, 2022). "Additionally, in univariable analysis, sex, IL-2R, IL-10, TNF-α, neutrophil percentage, lymphocyte percentage, NT-proBNP, hs-cTnI, coagulation disorder, and D-dimer were associated with kidney injury." (PMID 32850917, 2020). "Genetic factors such as proinflammatory interleukin Il-1ß or tumor necrosis factor genes, variants factor V Leiden, or prothrombin G20210A are also factors that influence fetal/neonatal bleeding involving vascular organization, inflammation, and coagulation disorders." (PMID 38541136, 2024). "The severity of cytopenia and coagulopathy have been shown to correlate with both the prognosis and TNF and IFN-γ-mediated cytokine storm flares." (PMID 34692727, 2021). "Most biomarkers are related to the immune system (SAA,TNF-∝, and IP-10) or coagulopathies (D-dimer, antithrombin, and VWF) and a few have already been established as cancer biomarkers (ACE2, IL-6, IL-4 and IL-2)." (PMID 32935101, 2020). "In univariable analysis, sex, clinical classification, IL-2R, IL-10, TNF-α, PCT, neutrophil percentage, lymphocyte percentage, NT-proBNP, hs-cTnI, eGFR, coagulation disorder, and D-dimer were associated with AKI." (PMID 32850917, 2020). "TNF-α exerts not only a cytotoxic effect on tumor cells and engages in a variety of pathophysiological processes, including viral and bacterial resistance, coagulation disorders, fever, inflammation, shock, multiorgan dysfunction, and formation of malignant fluid." (PMID 40771567, 2025). "TF level was also positively correlated with TNF-α, IL-1β, IL-6, and MPO levels and was negatively correlated with IL-10, indicating that the TF level was closely associated with the inflammatory factors, which may cause coagulation disorders." (PMID 32587471, 2020). "Neutralizing TNF activity by introducing a TNF receptor-IgG fusion protein, or an anti-TNF antibody, did not improve endotoxin-induced coagulopathy." (PMID 27408725, 2015).
end-stage renal disease (29 papers, 2012 to 2025). "It is well known that chronic inflammation is associated with elevated concentrations of proinflammatory cytokines, such as IL-1, IL-6, and TNF-α, in humans with end-stage renal failure." (PMID 37766698, 2023).
Hodgkins lymphoma (29 papers, 2006 to 2026). A heterogeneous group of malignant lymphoid neoplasms of B-cell origin characterized histologically by the presence of Hodgkin and Reed-Sternberg (HRS) cells in the vast majority of cases. "Two separate studies investigated how TNF-238 polymorphisms affected cancer susceptibility, one specifically focussing on Hodgkin lymphoma and the other covering a range of cancers (gastric, cervical, colorectal and renal)." (PMID 33985540, 2021). "The serum concentrations of cytokines such as interferon, tumor necrosis factor-α, and IL-6, which activate macrophages, were possibly elevated exclusively in the lymph nodes and spleen containing Hodgkin lymphoma cells." (PMID 39974298, 2025). "The tumor necrosis factor (TNF) family plays a crucial role in the pathogenesis of Hodgkin lymphoma." (PMID 39682256, 2024). "In Hodgkin’s lymphoma, the levels of TNF-α and its soluble receptors at diagnosis correlate with clinical features and outcome." (PMID 37610672, 2023). "Our results move forward our understanding of the putative role of the core-clock and TNF in the pathobiology of Hodgkin lymphoma, and highlight their influence in cellular proliferation and migration in lymphatic cancers." (PMID 30065253, 2018). "Tumor necrosis factor-α and interleukin-6 are expressed in Reed-Stemberg cells from patients with Hodgkin lymphoma." (PMID 26046344, 2015). "The tumor necrosis factor (TNF)‐receptor superfamily 8 receptor CD30 molecule is expressed in all tumor cells of Hodgkin lymphoma and anaplastic large cell lymphoma but is only weakly expressed in a small subset of large lymphoid cells in normal peripheral lymphoid tissues." (PMID 41123243, 2026). "HDAC11 negatively regulated the expression of interleukin-13/17 (IL-13/17) and tumor necrosis factor-alpha (TNF-α) in Hodgkin lymphoma, suggesting that HDAC11 inhibitors killed tumor cells by activating inflammatory responses, immune system activity, and apoptosis processes." (PMID 40421455, 2025). "A recent study on Hodgkin’s disease and anaplastic large cell lymphoma reported that tumor cells may aberrantly express TNF-α or thymus- and activation-regulated chemokines (TARC), which might attract a specific lymphocytic subset and CD4 + T-cell with a Th2 phenotype in particular." (PMID 31960941, 2020). "This review adopts a narrative approach to synthesize existing evidence on the role of the tumor necrosis factor (TNF) family in the pathogenesis and treatment of Hodgkin lymphoma (HL)." (PMID 39682256, 2024). "CD30 antigen is a transmembrane protein receptor of the tumor necrosis factor (TNF) family that is normally expressed in activated T and B cells, but is overexpressed in tumor cells of anaplastic large cell lymphoma (ALCL) and Hodgkin’s lymphoma." (PMID 25057429, 2013). "One patient, who received combination therapy of azathioprine and anti-TNFα, developed a Hodgkin lymphoma independent of EBV infection." (PMID 34768707, 2021). "Hodgkin lymphoma (HL) and Anaplastic Large Cell Lymphoma (ALCL), are forms of malignant lymphoma defined by unique morphologic, immunophenotypic, genotypic, and clinical characteristics, but both overexpress CD30, a 120 kDa member of the TNF/NGFR family." (PMID 18179710, 2008).
lupus-like syndrome (29 papers, 2010 to 2025). "Based on these few cases, SEC seems to increase the risk of lupus-like syndromes, but a similar phenomenon with an unclear molecular background was noticed in anti-TNF alpha inhibitors." (PMID 37232744, 2023). "The recently published cases of the coexistence of SLE and AS corresponded to drug-induced SLE or lupus-like syndrome associated with anti TNF treatment in SpA patients." (PMID 22400103, 2012). "Anti-TNFα therapies are the latest class of medications found to be associated, although rarely, with a “lupus-like” syndrome, which is however clinically distinct from classical DILE." (PMID 22937775, 2012). "Anti-TNFα therapies are the latest class of medications found to be associated with a “lupus-like” syndrome." (PMID 22937775, 2012). "While IL-6 (eg, tocilizumab) and TNF-α inhibitors show promise, they involve risks such as infections and lupus-like syndromes." (PMID 40643149, 2025). "Clinical experience revealed that a fraction of patients treated with TNF antagonists developed (increased) anti-dsDNA antibodies, in some cases with a concomitant lupus-like syndrome." (PMID 20096109, 2010).
Sleep apnea (29 papers, 2009 to 2025). An intermittent cessation of airflow at the mouth and nose during sleep is known as sleep apnea. "Increases in the concentration of circulating TNF-α after either sleep deprivation or sleep fragmentation (SF) appear to underlie excessive daytime sleepiness in patients with sleep apnea (OSA)." (PMID 23029133, 2012). "Sleep apnea episodes can cause hypoxemia and, consequently, an inflammatory state, as the low concentration of oxygen in the arterial blood stimulates the release of IL-6 and TNF-α." (PMID 36102458, 2023). "TNF-α should be incorporated into a sleep apnea scoring system to stratify the patients for early recognition of severe OSA." (PMID 32787816, 2020). "Based on prior evidence for their involvement in the regulation of sleep function and in pro-inflammatory physiology of sleep-disordered breathing, we selected TNF-α, IL-1β, and IL-6, to include as the basic explanatory inflammatory markers in our model." (PMID 23382975, 2013). "Higher levels of TNF-α levels are responsible for sleepiness in patients with sleep apnea, a condition that is characterized by prominent SF." (PMID 23029133, 2012). "Taken together, our findings show that recurrent arousals during sleep, as happens during sleep apnea, induce excessive sleepiness via activation of inflammatory mechanisms, and more specifically TNF-α-dependent pathways, despite preserved sleep duration." (PMID 22578011, 2012). "Shinji measured the plasma levels of inflammatory factors such as hypersensitive C-reactive protein(hs-CRP), IL-6, and TNF-α in 40 patients with sleep apnea syndrome and found that these inflammatory factor levels were correspondingly elevated in patients with sleep apnea syndrome." (PMID 39799348, 2025). "Similarly, the administration of etanercept, a TNF-alpha antagonist, achieved a significant reduction of sleepiness and sleep apnea and hypopnea events in obese patients with severe SAHS." (PMID 25760760, 2015). "TNF-α is an inflammatory cytokine that has been found elevated in patients with sleep apnea." (PMID 20628509, 2010). "Data supporting this hypothesis include the significant reduction of sleepiness and sleep apnea/hypopnea events in obese patients after the administration of etanercept, a TNF-alpha antagonist." (PMID 19262746, 2009). "Moreover, the pro-inflammatory cytokines IL-6 and TNF-α have been suggested to be mediators of excessive sleepiness in humans with pathologic conditions, e.g., sleep apnea and narcolepsy, and in experimentally induced sleepiness, i.e., following sleep deprivation." (PMID 25140521, 2014). "Others have demonstrated that the increase in TNF-α and IL-6 levels were accompanied by an increase in the AHI in patients with sleep apnea." (PMID 30213594, 2020). "For example, patients suffering from insomnia, fibromyalgia, obesity, sleep apnea (OSA) and various infections exhibit elevations in circulating TNF-α levels." (PMID 23029133, 2012). "That is, numerous inflammatory markers, including IL-6, IL-8, TNF-α, CRP, monocyte chemoattractant protein-1 (MCP-1), ICAM, selectins, VCAM, nitric oxide, and isoprostane, are elevated in body fluids of patients with sleep apnea." (PMID 25873764, 2015). "The present investigation is unique in its comprehensive analysis of IL-6, IL-8, IL-10, TNF-α, CRP, and S100B in a single cohort of sleep apnea patients compared to non-OSA controls in both serum and plasma." (PMID 37762178, 2023).
subarachnoid hemorrhage (29 papers, 2010 to 2025). A serious neurological disorder characterized by intracranial hemorrhage into the subarachnoid space. "Previous studies have shown that polymorphisms at position -308 and -863 in the promoter region of the TNF-α gene were associated with risks of subarachnoid hemorrhage (SAH) in multiple ethnicities." (PMID 20534169, 2010). "Previous studies have shown that TNF-α gene variation was associated with risks of subarachnoid hemorrhage in multiple ethnicities." (PMID 20534169, 2010). "Rn-C has also been shown to have antioxidant activities and can prevent interleukin-1b (IL-1b), interleukin-6 (IL-6), and tumor necrosis factor-alpha (TNF-α) mRNA expression in animals subjected to subarachnoid hemorrhage." (PMID 35631453, 2022). "Baicalin is further known to reduce the levels of AQP4, TNF-α, and IL-1β in rats with subarachnoid hemorrhage." (PMID 35764613, 2022). "The neuroprotective effects of necrostatin via necroptosis inhibition through TNFα related pathway have also been reported in subarachnoid hemorrhage." (PMID 35396550, 2022). "Pro-inflammatory cytokines, such as IL-1β, IL-6, and tumor necrosis factor-α, which have been shown to be activated in POEMS syndrome, are reportedly associated with cerebral vasospasm after subarachnoid hemorrhage." (PMID 34167480, 2021). "Fluoxetine has neuroprotective effects by reducing the production of proinflammatory factors, including NO, TNF-α, iNOS, and IL-1β, in early brain injury after subarachnoid hemorrhage." (PMID 34899324, 2021). "Supportively, one study showed that Mdivi-1 (1.2 mg/kg) injection after subarachnoid hemorrhage inactivated nuclear translocation of NF-κB and thereby reduced the levels of TNF-α, IL-6, and IL-1ß in ischemic-induced brain damage in MCAO rat models." (PMID 35002619, 2021). "The effects of ROF on cerebral inflammation developing in the subarachnoid hemorrhage model in rats were investigated and it was shown that it significantly reduced neurological damage and inflammatory cytokines IL1β, IL-6, and TNFα levels and the number of apoptotic neurons." (PMID 36865049, 2023). "Furthermore, protein level of TNF-α was significantly reduced in the left basal cortical of subarachnoid hemorrhage rats after receiving MCC95028." (PMID 34588488, 2021). "GAS treatment ameliorates subarachnoid hemorrhage induced neurological deficit, oxidative stress, inflammation and apoptosis by increasing Nrf2 activation and suppressing the expressions of interleukin (IL)-1β and tumor necrosis factor (TNF)-α." (PMID 32560430, 2020). "However, the subarachnoid hemorrhage results in release of pro-inflammatory cytokines such as IL-1, IL-6, and TNF-α from microglia and macrophages, resulting in local and systemic inflammation." (PMID 32326289, 2020). "Interestingly, recent study showed that glibenclamide could decrease TNF-α and NF-κB activation after subarachnoid hemorrhage." (PMID 25077824, 2014). "Subcutaneous administration of roflumilast (1 mL saline containing 3% DMSO, 3 mg/kg) decreased tumor necrosis factor-α (TNF-α), interleukin-1β (IL-1β), and IL-6 levels and the number of apoptotic neurons in the brain following subarachnoid hemorrhage." (PMID 37525115, 2023). "In a model of subarachnoid hemorrhage in rats, a very recent study found that AE1-329, an EP4 receptor agonist, significantly reduced BBB damage, edema, and expression of IL-1β, IL-6, and TNF-α." (PMID 29527151, 2018).
venous thromboembolism (29 papers, 2010 to 2026). Occlusion of the lumen of a vein by a thrombus that has migrated from a distal site via the blood stream. "JAK inhibitor use was associated with a slightly higher risk of venous thromboembolism compared with TNF antagonist use; the overall incidence of serious adverse events was low." (PMID 40928778, 2025). "The present study comprehensively examined associations of TNF levels with most common CVDs amongst a general population and revealed positive associations of TNF levels with atherothrombotic disease and venous thromboembolism." (PMID 32805626, 2020). "Additionally, this substance class is associated with an increased risk of venous thromboembolism compared to placebo or tumor necrosis factor (TNF) inhibitors." (PMID 40430355, 2025). "However, a recent longitudinal cohort study based on the German register RABBIT revealed that anti-TNF agents decreased the risk of serious venous thromboembolism events compared to csDMARDs medicine, which is in line with our finding." (PMID 32805626, 2020). "Additionally, there may have been reluctance to prescribe tofacitinib following the European reevaluation of May 2019 of the A3921133 clinical study, which revealed an increased risk of severe venous thromboembolism at a dosage of 10 mg twice a day compared with anti-TNF." (PMID 39200750, 2024). "IL-6 and TNF-α are familiar cytokines and some studies suggested that inflammation played a key role in the pathogenesis of venous thromboembolism." (PMID 36717769, 2023). "Additionally, a European re-evaluation of tofacitinib was carried out in May 2019 following the interim analyses of clinical study A3921133 that demonstrated an increased risk of severe venous thromboembolism compared to tumor necrosis factor inhibitors at a dosage of 10 mg twice daily." (PMID 33081099, 2020). "Even though inflammation and the innate immune system have an important role in venous thromboembolism, the link between TNF and thrombogenesis remains unclear." (PMID 32805626, 2020). "Patients with venous thromboembolism demonstrate increased levels of proinflammatory cytokines including interleukin-6, interleukin-8, and TNF-alpha and the formation of blood clots has been shown to lead to thrombus fragmentation and generation of proinflammatory fibrin breakdown products." (PMID 26078907, 2015). "It aids in preventing venous thromboembolism, particularly in patients aged between 40 and 70 years, by inhibiting the mTOR cell pathway, suppressing platelet aggregation, and modulating immune responses, thereby reducing inflammatory markers such as TNF-alpha and IL-6." (PMID 40599143, 2025). "The data associating anti-TNF agents with hypercoagulablity are still in the preliminary stages, but these cases suggest that etanercept-induced LAC positivity may be a contributing factor to venous thromboembolism." (PMID 20157435, 2010). "The results showed an increased risk of death, malignancy, major adverse cardiac events (MACE), and venous thromboembolism (VTE) in tofacitinib-treated patients (both 5mg and 10 mg arms) compared to those treated with TNF inhibitors." (PMID 35432355, 2022).